HAR1A (highly accelerated region 1A)
Synonyms: HAR1F; NCRNA00064; LINC00064
Gene: Long non-coding RNA gene on chromosome 20 (63,102,205 to 63,104,421, forward strand). Ensembl gene ENSG00000225978.
Diseases named in the same sentence as HAR1A in open-access papers:
HAR1A is named in the same sentence as 33 diseases in open-access papers, as found by Europe PMC text mining. Sharing a sentence is not in itself a finding about the gene and the disease. The quoted sentences say what the papers report.
glioma (13 papers, 2017 to 2025). A benign or malignant brain and spinal cord tumor that arises from glial cells (astrocytes, oligodendrocytes, ependymal cells). "All together, these results suggested that high PVT1 expression and low HAR1A expression were associated with poor survival outcome of glioma patients." (PMID 29108264, 2017). "In this study, we have shown that HAR1A is negatively regulated by REST in glioma cells, and that the expression of these two molecules has an opposite prognostic significance in glioma patients." (PMID 39602392, 2024). "First, we studied the role of HAR1A in a limited collection of cell types (glioma and glioblastoma)." (PMID 39602392, 2024). "Taken together, these data and the results of the previous section show that REST inhibits the expression of HAR1A in glioma cells, and that REST appears to be essential for the proliferation of GBM cells." (PMID 39602392, 2024). "Higher REST expression predicts worse prognosis in low-grade gliomas (the opposite is true for HAR1A)." (PMID 39602392, 2024). "HAR1A expression and subcellular localization were studied in glioblastoma and paediatric glioma cells." (PMID 39602392, 2024). "In the lower grade glioma dataset, we found that a poorer prognosis of patients correlated with low expression of HAR1A and HAR1B, and with high expression of REST." (PMID 39602392, 2024). "On the other hand, lncRNA HAR1A acts to suppress the progression of diffuse glioma and is expressed at low levels in glioma." (PMID 36819921, 2023). "Up-regulation of HAR1A is thought to improve the survival of diffusing glioma patients who received chemotherapy and radiotherapy." (PMID 35574307, 2022). "Our analysis indicated that JAG1, PVT1, H19, and HAR1A were aberrantly expressed in IDH mutant gliomas and were core lncRNA genes in regulating the expression of protein-encoding gene in IDH mutant gliomas." (PMID 33329315, 2020). "Multivariate analysis showed that low HAR1A expression was an independent prognosis factor for OS of glioma patients (HR = 1.6, p = 0.021)." (PMID 32802843, 2020). "Survival of glioma patients with low HAR1A expression was significantly worse than that with high expression (both P <0.0001)." (PMID 29108264, 2017). "As expected, REST suppresses the expression of HAR1A in both pediatric and adult glioma cells." (PMID 39602392, 2024). "It is therefore conceivable that REST promotes glioma progression by down-regulating HAR1A." (PMID 39602392, 2024). "To understand whether these expression levels could be functionally relevant, we compared HAR1A expression in glioma vs other cell types, using the human Expression Atlas." (PMID 39602392, 2024). "Our results show that REST and HAR1A are negatively correlated in gliomas." (PMID 39602392, 2024). "Our results seem to exclude an in vitro function for HAR1A in gliomas." (PMID 39602392, 2024). "We found that several lncRNAs, namely, AL606760.2, H19, MALAT1, PVT1 and SBF2-AS1 may function as glioma risk factors, whereas AC068643.1, AC079228.1, DGCR5, FAM13A-AS1, HAR1A and WDFY3-AS2 may have protective effects." (PMID 36819921, 2023). "Moreover, the down-regulation of PVT1 and up-regulation of HAR1A improved the survival of glioma patients that received chemotherapy and radiotherapy." (PMID 36819921, 2023). "In addition, glioma patients with high PVT1 expression or low HAR1A expression is reported to be prognostic of poor survival in glioma patients." (PMID 36819921, 2023). "Among the nine EMT-related lncRNAs identified in this study, LINC00900, MIR210HG, MIR22HG, PVT1, and SNHG18 were positively correlated with glioma malignancy, whereas HAR1A, LINC00641, SLC25A21-AS1, and SNAI3-AS1 were negatively correlated with glioma malignancy." (PMID 34288803, 2021).
glioma (continued). "Subsequent multivariate analysis results revealed that high PVT1 expression (HR: 2.539, P <0.001) and low HAR1A expression (HR: 1/0.625=1.6, P = 0.021) were the independent prognosis factors for survival of glioma patients, in addition to increased age, high KPS and grade." (PMID 29108264, 2017). "The forest plot shows that EPB41L4A.AS1, GDNF.AS1, HAR1A, LINC00237, SLC25A21.AS1, SNA13.AS1, and WDFY3.AS2 are the protective factors with HR < 1, while LINC00092, LINC00265, LINC00339, LINC00665, PAXIP1.AS2, SNHG16, SNHG9 and SOCS2.AS1 are risk factors with HR>1 in glioma patients." (PMID 35273128, 2022). "HAR1A was expressed specifically in Cajal–Retzius neurons in the developing human neocortex, and a previous study reported that HAR1A could act as a prognostic marker for isocitrate dehydrogenase mutant glioma." (PMID 34194477, 2021). "To analyze the relationship between HAR1A and HAR1B with REST in gliomas, we began by correlating their RNA expression in lower grade gliomas and glioblastoma, using the Cbio Portal." (PMID 39602392, 2024). "The genes most significantly coexpressed with HAR1A and HAR1B in lower grade gliomas were analyzed in the publicly available ontology resource Metascape." (PMID 39602392, 2024). "After determining the expression of HAR1A and HAR1B in the glioma cell lines, we identified their subcellular localization." (PMID 39602392, 2024). "Our results confirmed that HAR1A and HAR1B are negatively correlated with REST expression in pediatric gliomas." (PMID 39602392, 2024). "After showing that HAR1A and HAR1B have positive prognostic roles in lower grade gliomas, we determined possible downstream pathways and upstream regulators of the lncRNAs, using gene ontology." (PMID 39602392, 2024). "A nine-EMT-related lncRNAs (HAR1A, LINC00641, LINC00900, MIR210HG, MIR22HG, PVT1, SLC25A21-AS1, SNAI3-AS1, and SNHG18) signature was identified in patients with glioma." (PMID 34288803, 2021). "Furthermore, survival curve and Cox regression analyses showed that glioma patients with high PVT1 expression or low HAR1A expression had poor survival outcome, aberrantly expressed PVT1 and HAR1A could be the independent prognosis biomarkers for diffuse glioma patients." (PMID 29108264, 2017). "Further analysis of TCGA and GEO data revealed that the expressions of PVT1 and CYTOR were up-regulated, while HAR1A and MIAT expressions were down-regulated in gliomas." (PMID 29108264, 2017). "Our studies first identified differentially expressed lncRNAs in glioma based on gene expression profiling, and focused on the lncRNAs PVT1, CYTOR, HAR1A and MIAT for further analysis." (PMID 29108264, 2017). "This study focused on identifying differentially expressed lncRNAs in gliomas based on gene expression profiling, and chose certain lncRNAs PVT1, CYTOR, HAR1A and MIAT, which changed with significant differences." (PMID 29108264, 2017). "Following the linear regression analysis of HAR1A, HAR1B, and REST, we determined whether aberrant expression of these lncRNAs and REST impacted glioma patient prognosis, using a Kaplan Meier analysis." (PMID 39602392, 2024). "Hence, the objectives of this study are to investigate the clinical significance of REST, HAR1A, and HAR1B expression in pediatric and adult gliomas and their functional roles in key cancer hallmarks (including cell survival, proliferation and migration)." (PMID 39602392, 2024). "Survival analyses indicated that glioma patients with low PVT1 expression and high HAR1A expression could benefit more from chemotherapy and radiotherapy." (PMID 29108264, 2017). "Glioma patients with high PVT1 expression and low HAR1A expression had poor survival outcome, up-regulated PVT1 and down-regulated HAR1A could be the independent prognosis factors for glioma patients." (PMID 29108264, 2017). "Our overexpression studies did not corroborate a tumour suppressive role for HAR1A in glioma." (PMID 39602392, 2024).
glioma (continued). "HAR1A could be potentially used as a prognostic biomarker for HCC and glioma." (PMID 33329315, 2020). "Kaplan-Meier survival curve and Cox regression analyses showed that glioma patients with high PVT1 expression or low HAR1A expression had poor survival outcome, aberrantly expressed PVT1 and HAR1A could be the independent prognosis biomarkers for glioma patients." (PMID 29108264, 2017). "Glioma patients with low HAR1A expression had poor survival, down-regulated HAR1A, not MIAT, could be an independent prognosis biomarker for diffuse gliomas." (PMID 29108264, 2017). "Notably, HAR1A-downstream pathways in gliomas have not been explored so far." (PMID 39602392, 2024). "The expressions of HAR1A and MIAT were significantly decreased in glioma samples compared to non-tumor controls (both P <0.001)." (PMID 29108264, 2017). "We found that HAR1A and HAR1B have a significant positive correlation in both datasets, HAR1A and REST have a significant negative correlation in both datasets, and HAR1B and REST have a significant negative correlation in lower grade gliomas, but unexpectedly, do not correlate in the GBM dataset." (PMID 39602392, 2024). "Taken together, these results suggest that HAR1A and REST are negatively correlated in all glioma subtypes analyzed, and that the expression of these molecules is of prognostic relevance in adult lower grade gliomas, but not in the most aggressive gliomas (DIPG and GBM)." (PMID 39602392, 2024).
oral cancer (6 papers, 2022 to 2025). "HAR1A acted as a tumor suppressor for oral cancer by regulating the ALPK1/BRD7/myosin IIA axis in oral cancer." (PMID 35740511, 2022). "There are very few publications regarding this molecule to date, but several studies have suggested HAR1A as a tumor suppressor in oral cancer, hepatocellular carcinoma (HCC), and diffuse glioma." (PMID 35740511, 2022). "Moreover, lncRNA HAR1A was found to retard the progression of oral cancer by inhibiting the ALPK1/BRD7/myosin IIA axis." (PMID 38688909, 2024). "Other teams and we have shown that lncRNA HAR1A is a tumor suppressor in several cancers, including HCC, oral cancer, and NSCLC." (PMID 38688909, 2024). "In the nucleus of cancer cells, HAR1A functioned upstream of the signaling pathway, and knockdown of HAR1A promoted ALPK1 expression and downregulated myosin IIA and BRD7, leading to inflammation and oral cancer progression." (PMID 36139553, 2022). "HAR1A is a tumor suppressor, and in oral cancer patients, knockdown of HAR1A promotes the expression of ALPK1 and leads to oral cancer progression." (PMID 35757472, 2022). "In oral cancer cells and monocytes, the expression of TNF-α and CCL2 was increased after HAR1A knockdown and decreased after ALPK1 knockdown." (PMID 36139553, 2022).
Huntington disease (4 papers, 2012 to 2022). Huntington disease (HD) is a rare neurodegenerative disorder of the central nervous system characterized by unwanted choreatic movements, behavioral and psychiatric disturbances and dementia. "HAR1A is associated with the central nervous system, Huntington’s disease, Alzheimer’s disease, and SCZ." (PMID 36385761, 2022). "Previous studies reported that HAR1A could be repressed transcriptionally by REST, and HAR1 expression was lower in the striatum of Huntington’s disease patients than normal controls." (PMID 29108264, 2017).
breast carcinoma (3 papers, 2017 to 2020). "In human cancers, LncRNA HAR1A had been linked to the recurrence of breast cancer." (PMID 29108264, 2017). "Similar to our results, a 9-lncRNA signature consisting of HAR1A and its upregulation predicted breast cancer recurrence and served as a prognostic marker for breast cancer." (PMID 32368310, 2020).
hepatocellular carcinoma (3 papers, 2020 to 2022). A malignant tumor that arises from hepatocytes. "Previous studies reported that the HAR1A expression levels were reduced in tissue specimens coinfected with hepatocellular carcinoma (HCC) and that low expression of HAR1A in patients with HCC was significantly associated with advanced histological grade and TNM stage." (PMID 33329315, 2020).
glioblastoma (2 papers, 2017 to 2024). The most malignant astrocytic tumor (WHO grade IV). "The results implied that CYTOR and MIAT may be associated with amplification of PDGFRA and IDH1 mutations, HAR1A may be related with neuron markers in glioblastomas." (PMID 29108264, 2017). "It’s consistent with our result that HAR1A was preferentially expressed in the neural subtypes of glioblastoma." (PMID 29108264, 2017). "We applied the classification criterion to describe the expression of PVT1, CYTOR, HAR1A and MIAT in glioblastoma subtypes." (PMID 29108264, 2017). "To further investigate the clinical relevance of REST and HAR1A/HAR1B expression, we compared the expression of these genes in a publicly available dataset of glioblastoma samples taken from MRI contrast enhancing (CE) tumour core and non-enhancing (NE) tumour periphery regions." (PMID 39602392, 2024). "Due to the strong negative correlation between REST and HAR1A, we have hypothesized that the oncogenic activity of REST in glioblastoma was at least in part mediated by HAR1A silencing." (PMID 39602392, 2024).
lung carcinoma (2 papers, 2022 to 2024). "In conclusion, our results indicated that HAR1A deficiency disables the ubiquitination and proteasomal degradation of ANXA2 to activate the NF-κB pathway, leading to lung cancer progress." (PMID 38688909, 2024).
non-small cell lung carcinoma (2 papers, 2022 to 2024). A group of at least three distinct histological types of lung cancer, including non-small cell squamous cell carcinoma, adenocarcinoma, and large cell carcinoma. "We previously reported lncRNA HAR1A as a tumor suppressor in non-small cell lung cancer (NSCLC)." (PMID 38688909, 2024).
astrocytoma (1 paper, 2017). "GBM also displayed statistically lower HAR1A and MIAT expression as compared with oligodendroglioma (P =0.002 and P =0.008), oligoastrocytoma (P =0.016 and P =0.044), and astrocytoma (P =0.009 and P =0.054)." (PMID 29108264, 2017).
autism (1 paper, 2024). Persistent deficits in social interaction and communication and interaction as well as a markedly restricted repertoire of activity and interest as well as repetitive patterns of behavior. "Finally, in a study focusing on the network of miRNA sponges for various neuropsychiatric disorders, including autism, HAR1A was identified as a candidate for this role in the autism spectrum disorder and was also found to be downregulated in AD." (PMID 39086756, 2024).
colorectal cancer (1 paper, 2022). A primary or metastatic malignant neoplasm that affects the colon or rectum. "Among all lncRNAs unknown association with colorectal cancer on the MNDR dataset, lncRNA HAR1A is inferred to link to colorectal cancer with the highest association scores." (PMID 36744179, 2022).
eczema (1 paper, 2024). "AD, also known as eczema, produces dry, itchy, and red skin; the HAR1A gene is implicated in AD." (PMID 38792557, 2024).
epilepsy (1 paper, 2016). A brain disorder characterized by episodes of abnormally increased neuronal discharge resulting in transient episodes of sensory or motor neurological dysfunction, or psychic dysfunction. "The HAR1A gene is considered an accelerated evolution gene for human brain development with molecular defects of the gene leading to psychotic and disruptive disorders; the genes CHRNA4 and KCNQ2 also deleted have been associated with ASD and epilepsy." (PMID 27651829, 2016).
lung adenocarcinoma (1 paper, 2022). A carcinoma that arises from the lung and is characterized by the presence of malignant glandular epithelial cells. "To further elucidate the underpinning mechanism by which lncRNA HAR1A promotes NSCLC tumorigenesis, we conducted GSEA to screen the potential downstream signaling pathway in lung adenocarcinoma with TCGA datasets." (PMID 35740511, 2022).
lymph node metastasis (1 paper, 2023). "In our panel, HAR1A also acted as a negative factor for early lymph node metastasis in GC." (PMID 37691031, 2023).
myocardial infarction (1 paper, 2017). Gross necrosis of the myocardium, as a result of interruption of the blood supply to the area, as in coronary thrombosis. "Among the down-regulated lncRNAs, HAR1A (highly accelerated region 1A) and MIAT (myocardial infarction associated transcript) were presented with high value of an absolute log2(fold-change) (logFC =-2.873, P =2.98E-11 for HAR1A; logFC =-2.459, P =1.61E-07 for MIAT)." (PMID 29108264, 2017).
ovarian carcinoma (1 paper, 2020). A malignant neoplasm originating from the surface ovarian epithelium. "For ovarian cancer patients treated with platin, five lncRNAs including LINC01134, HAR1A, LINC01139, LINC-PINT, and DNM3OS were significantly associated with PFS." (PMID 32260415, 2020).
prostate carcinoma (1 paper, 2024). A carcinoma that arises from epithelial cells of the prostate gland. "We therefore measured HAR1A levels in prostate cancer cells (LNCaP), finding that HAR1A has a higher expression in the prostate cancer cells, compared to GBM and DMG cells." (PMID 39602392, 2024).
serous ovarian cancer (1 paper, 2020). "For serous ovarian cancer patients, three lncRNAs including HAR1A, LINC00886, and LINC-PINT were significantly associated with PFS." (PMID 32260415, 2020). "For serous ovarian cancer patients treated with platin, five lncRNAs including HAR1A, LINC00886, LINC01139, LINC-PINT, DNM3OS were significantly associated with PFS." (PMID 32260415, 2020).
cancer (10 papers, 2017 to 2025). A tumor composed of atypical neoplastic, often pleomorphic cells that invade other tissues. "Thereby, we identified a novel fine-tuning mechanism interpreting how the loss of HAR1A promoted cancer development and how HAR1A was decreased in NSCLC." (PMID 38688909, 2024). "REST function was also studied in these cells, by observing the effects of gene silencing on: (I) HAR1A expression; (II) cancer cell proliferation, apoptosis, migration; (III) expression of neural differentiation genes." (PMID 39602392, 2024). "The m6A modification levels of HAR1A were increased in cancer cells, while YTHDF2 was responsible for recognizing m6A modification in the HAR1A, leading to the disintegration of this lncRNA." (PMID 38688909, 2024). "Compared to normal epithelial cells, several cancer cell lines exhibited decreased expression of HAR1A." (PMID 38688909, 2024). "The risk signature of our study included 8 lncRNAs (CRNDE, LINC00844, FAM66C, TUBA3FP, SNHG8, HAR1A, LINC00641, and MYCNOS), and previous evidence has suggested that these lncRNAs are closely linked to the occurrence and development of cancer." (PMID 35832170, 2022). "Therefore, decreased HAR1A in NSCLC potentiates cancer growth and metastasis by upregulating the ANXA2." (PMID 38688909, 2024). "Having identified the subcellular localization of the lncRNAs in the cell, we then investigated whether REST silencing and HAR1A overexpression affect the cell proliferation and apoptosis of cancer cells." (PMID 39602392, 2024). "Therefore, decreased HAR1A in NSCLC potentiates cancer growth and metastasis by upregulating the ANXA2/NF-κB axis." (PMID 38688909, 2024).